IL6 (interleukin 6)
Diseases named in the same sentence as IL6 in open-access papers (continued):
Sharing a sentence is not in itself a finding about the gene and the disease.
tumor (continued). "The production of cancer-related factors supporting IL-6 production by the tumour correlate with its propensity to establish distant metastases." (PMID 20808314, 2010). "Epithelial NF-κB activation results from the rich abundance of IL1β, TNFα and TLR-agonists in the tumour microenvironment, and IL1β, TNFα and many other cytokines and chemokines (i.e. IL6, CXCL2, CCL2 and CCL20) are transcriptional targets for NF-κB." (PMID 20478049, 2010). "Interleukin-6 (IL-6) is a pleiotropic cytokine produced by T cells, B cells, monocytes, fibroblasts, endothelial cells and several types of tumor cells." (PMID 24281094, 2010). "IL-6 is also a regulator of various chronic inflammatory processes that can create better conditions for tumor growth." (PMID 20184737, 2010). "Consistent with predictions from our in vitro studies, a reduction in tumor cell growth was observed with both MzChA-1 and Mz-IL-6 xenografts." (PMID 21179572, 2010). "We have previously shown that blocking NFκB in HEp2 tumor cells decreased IL-6 and IL-8 secretion substantially and resulted in an increased sensitivity of HEp2 tumor cells to NK cell mediated cytotoxicity." (PMID 20661281, 2010). "HCC arises most frequently in the setting of chronic liver inflammation and moreover cytokines, such as IL-6, produced in the inflammatory tumor microenvironment stimulate the growth of cancer cells and tumor invasiveness." (PMID 20723213, 2010). "Expression of HGF and IL-6 in the tumor tissues of group I increased dramatically in comparison with that in the control group." (PMID 20667141, 2010). "HBD-3 stimulated the expression of tumor-promoting cytokines, including interleukin-1α (IL-1α), IL-6, IL-8, CCL18, and tumor necrosis factor-α (TNF-α) in macrophages derived from human peripheral blood monocytes." (PMID 20544025, 2010). "IL-6 is produced by a variety of cells such as T cells, B cells, monocytes, macrophages, fibroblasts, endothelial cells, and several tumor cells." (PMID 20374625, 2010). "ANXA1 expression in prostate carcinogenesis correlates with enhancing tumor aggressiveness through increasing IL-6 expression and activity." (PMID 20927350, 2010). "A correlation between IL-6 levels and recurrence was shown, leading to the conclusion that IL-6 can be an indicator of tumor aggressiveness." (PMID 20184737, 2010). "DCs expressed low but detectable levels of CD277, which were further up-regulated upon incubation with tumor-derived ascites or inflammatory IL-6." (PMID 21113407, 2010). "Our finding that MSC secreted paracrine factor, IL-6, enhances early stage Skov-3 proliferation emphasizes the importance of a proper microenvironment for tumor growth." (PMID 19352430, 2009). "MCP-1/CCL2 recruits TAM to the tumor site, and these cells release IL-6 and contribute to tumor stroma formation and angiogenesis." (PMID 19582164, 2009). "IL-6 plays an important role in regulating self-renewal and differentiation of stem cells, as well as tumor growth." (PMID 19907660, 2009). "High levels of serum IL-1β and IL-6 levels correlated with delayed tumor progression in animals bearing 4T1 tumors treated with mcr84 and GU81, whereas low levels of these cytokines corresponded to tumor progression." (PMID 19888452, 2009). "The interleukin-6 (IL-6) and the chemokine CCL5 are implicated in the development and progression of several forms of tumours including that of the prostate." (PMID 19242540, 2009). "With regard to the autocrine pathway, IL-6 activated the production of IL-6 by tumor cells with the IL-6 receptor." (PMID 19457231, 2009). "Our results suggest the dependence of in vitro Skov-3 tumor cell proliferation is due to the presence of tumor-stimulated MSC secreted IL6." (PMID 19352430, 2009). "For example, Grivennikov and co-workers demonstrate that Il6−/− mice exhibit decreased tumor multiplicity and load compared to WT mice after AOM/DSS treatment yet these mice displayed more severe intestinal inflammation than WT mice." (PMID 19551144, 2009).
tumor (continued). "Tumor cells secreting high levels of IL-6 and MIP-1α were found to be recruited to the bone marrow, where the balance between osteoblasts and osteoclasts was altered, leading to a series of changes in the endosteal and vascular niches." (PMID 19497133, 2009). "Perhaps it is the tumor expression of IL-23, IL-6, epidermal growth factor or Janus kinase 2 or an undefined factor that ultimately regulates the expression of PBMC p-STAT-3 levels, but this was not determined in our current study." (PMID 19900287, 2009). "Inconsistent with the in vitro finding, serum concentration of PSA, which was adjusted based on tumour volume, in intact mice bearing LNCaP/IL-6#1 tumour before castration was significantly lower than that in mice bearing LNCaP/Co tumour." (PMID 19844233, 2009). "The proposed mechanism of IL-6/sIL-6Rα complex is to activate the various immune cells indicated via IL-6Rβ, which in combination would lead to potent anti-tumor effects (Th1 immune responses)." (PMID 19497133, 2009). "In the admixed MSC/Skov-3 tumors, there was a widespread presence of the IL-6 staining that was found in stronger concentrations along the leading edges of the tumor." (PMID 19352430, 2009). "The reciprocal regulation of MSC conditioning on stimulated Skov-3 tumor showed increases in IL-6, TGF-β, VEGF and HGF secretion." (PMID 19352430, 2009). "In other words, IL-6 complexed with sIL-6Rα has demonstrated qualitatively different biological activity from IL-6 alone in stimulating long-lasting anti-tumor immunity." (PMID 19497133, 2009). "The acute phase synthesis of CRP is upregulated by proinflammatory cytokines as interleukin-1, interleukin-6, and tumour necrosis factor, which act as autocrine growth factors for neoplasm." (PMID 27956962, 2009). "We noted that IL-6 levels were significantly correlated with IL-6 levels, and tumor size with higher IL-6 levels was detected in tumors sized ≥ 5 cm (P = 0.0012)." (PMID 19457231, 2009). "IL-1 and IL-6 produced by tumor cells, fibroblasts, and APCs are potent in expanding memory TH17 cells." (PMID 20017942, 2009). "For animals treated with mcr84 or GU81, we found that decreases in serum levels of IL-1β and IL-6 were highly correlative with changes in tumor size in the presence of anti-VEGF therapy." (PMID 19888452, 2009). "That is why we mainly focused to see the role of cadmium on influencing the cellular expression of Cox-2, IL-6 and their down stream mediators, because of the fact that along with inflammation, these are the two known parameters of tumor development." (PMID 19523218, 2009). "Detection of membranous and soluble forms of gp130 and gp80 and detection of IL-6 in tumour cell lines." (PMID 19956602, 2009). "With regard to the paracrine pathway, IL-6-stimulated stromal cells promoted the secretion of tumor growth and adhesion molecules containing VEGF and hepatocyte growth factor (HGF)." (PMID 19457231, 2009). "estrogen, is repressive for the expression of inflammatory genes, such as IL-6, leading to tumor suppression." (PMID 19686584, 2009). "In an autocrine system, IL-6 was known to regulate tumor cells proliferation and secretion of metalloproteinases, which are involved in tumor invasion and metastasis." (PMID 19497133, 2009). "Compared with the 4T1 tumor-bearing Balb/c mice, significant increase in the levels of M-CSF (1.5 fold), IL-17 (1.5 fold), TNF-α, VegF, and IL-6 (1.2 fold) was observed in the 4T1 tumor-bearing arthritic mice." (PMID 19643025, 2009). "This enhanced sensitivity of LNCaP/IL-6#1 to androgen withdrawal was more remarkable in vivo; that is, after castration, LNCaP/IL-6#1 tumour rapidly regressed and completely disappeared." (PMID 19844233, 2009). "The inflammatory cytokine interleukin-6 (IL-6) enhances tumor growth in CC by altered gene expression via autocrine mechanisms." (PMID 27933122, 2009).
tumor (continued). "Further, bone marrow mesenchymal stem cells (MSC) tend to secrete a high level of IL-6, which is known to play a pivotal role in the marrow space for further tumor metastatic dissemination." (PMID 19497133, 2009). "The mRNA and protein expression of IL-6 and its two receptor subunits gp130 and gp80 was assessed in a panel of nine haematologic tumour cell lines, using flow cytometry, ELISA and RT-PCR, comparing with the triple positive control U266 cells." (PMID 19956602, 2009). "Before androgen ablation, despite the lack of a significant difference in the in vitro growth between LNCaP sublines, LNCaP/IL-6#1 tumour grew significantly faster than LNCaP/Co tumour." (PMID 19844233, 2009). "We confirmed the presence of HGF, EGF and IL-6 within the tumor stimulated MSC population that we identify as TAF." (PMID 19352430, 2009). "OSMR is a receptor of Oncostatin M (OSM), an interleukin-6 (IL-6)-type cytokine identified as a potent suppressor of tumor cells." (PMID 19662090, 2009). "For this purpose, anti-IL-6 antibodies were added to LNs of 4T1 tumour-bearing mice, restimulated with Mage-b." (PMID 18728665, 2008). "Raised levels of CRP, an acute phase protein (APP), and proinflammatory cytokines, especially IL-6, are strong, independent prognostic factors for survival in a number of tumour types including breast, renal cell, prostate and colorectal cancers." (PMID 18059400, 2008). "This assistance involves the upregulation of IL-1, IL-6, IL-8, TNFα and MMPs that promote surrounding tissue destruction, leading to tumour invasion and ultimately metastasis." (PMID 19014637, 2008). "In NSCLC cell lines IL-6 has been shown to be involved in tumour cell proliferation, in tumour promotion and progression." (PMID 18682839, 2008). "This phenomenon is consistent with previous findings that tumor cells secrete many immunosuppressive cytokines and chemokines (IL-6, IL-10, and TGF-β)." (PMID 18793383, 2008). "In the model of DEN-induced hepatocarcinogenesis, the estrogen-regulated difference in IL-6 production bymale versus female Kupffer cells entirely accounts for the gender differencesin tumor incidence." (PMID 18615187, 2008). "When monocytes are stimulated in co-culture with HNSCC tumour cells, high levels of both IL-6 and MCP-1 can be detected in supernatants." (PMID 18234094, 2008). "Tumour biopsies were immunohistochemically stained for IL-6 and TGF-β1, and immunoreactivity was quantified (grade 1–4)." (PMID 18682839, 2008). "Monocytes are recruited by chemokine gradients to migrate from circulation into tumour tissues where a further differentiation to TAMs or DCs takes place under the regulation of environmental signals of such as IL-6." (PMID 18234094, 2008). "Conversely, in tumours, studies have demonstrated an increase in the expression of some ABC superfamily transporters on tumour cells in response to IL-6, where they produce the multidrug-resistant tumour phenotype." (PMID 18059400, 2008). "As administration of exogenous IL-6 to cancer cells in vitro induces drug resistance, the expression of multidrug resistance genes was assessed within the tumour at different time points." (PMID 18059400, 2008). "Inflammatory cytokines such as TNF-α, IL-1 and IL-6 are involved in angiogenesis, which is fundamental step in tumour development." (PMID 18201386, 2008). "Additional release of IL-6 or TGF-β1 into the blood circulation as a result of radiation-induced lung injury is often superimposed by the variable cytokine production of the tumour and thus will be difficult to detect." (PMID 18682839, 2008). "Compared to the rather intense staining for TGF-β1 in most of the analyzed tumour biopsies, the IL-6 staining of the tumour specimens was generally weaker." (PMID 18682839, 2008).
tumor (continued). "Statistically significant correlations were observed between the tumour response and IL-6 and TGF-β1 plasma levels, respectively, assessed at the same time-points during follow-up (p = 0.019 and p<0.0001, trend tests based on mixed model analysis)." (PMID 18682839, 2008). "In a previous study, we found that IL-6 and TGFβ are highly produced by the 4T1 primary tumours and metastases." (PMID 18728665, 2008). "To apply the findings made in HeLa cells regarding PDT-dependent changes in IL-6 regulation of cell proliferation to an in vivo tumour model, we chose the murine colon cell line Colon26." (PMID 17987036, 2007). "Endogenous and exogenous IL-6 and exogenous OM up-regulated cell growth and enhanced resistance of PC-3 tumor cells to both etoposide and cisplatin." (PMID 17374166, 2007). "Our current study demonstrates for the first time that significant amounts of sIL-6Rα, capable of mediating the effects of PDT-induced IL-6, can be expected to be generated in the tumour environment." (PMID 17987036, 2007). "Preclinical studies show thattumor-induced inhibition of DC differentiation is mediated by tumor-derivedsoluble factors such as IL-10, IL-6, M-CSF, prostaglandins, and vascular endothelialgrowth factor (VEGF)." (PMID 18320010, 2007). "Cells of gp130+/IL-6Rα−/low phenotype, such as endothelial and epithelial cells, in the post-PDT tumour environment can be affected by the presence of IL-6 via trans-signalling mechanisms." (PMID 17987036, 2007). "To address the question of potential effects of IL-6 trans-signalling on the proliferation of PDT-surviving tumour cells, we incubated HeLa cells with IL-6, or Hyper-IL-6, following graded PDT doses and assessed survival and proliferation." (PMID 17987036, 2007). "Soluble interleukin-6 receptor-α (IL-6Rα) (sIL-6Rα) and IL-6 were released by leucocytes in the presence of conditioned medium from PDT-treated tumour cells." (PMID 17987036, 2007). "Probably directed in part by PGE2, based on reduced production of anti-tumor Th1 cytokines (TNFα, IFNγ and IL-2) and increased production of Th2 cytokines (IL-4, IL-10 and IL-6)." (PMID 19455240, 2007). "The IL-6 trans-signalling-mediated attenuation of cell proliferation was also effective in vivo detectable by an improved Colon26 tumour cure by PDT combined with Hyper-IL-6 treatment." (PMID 17987036, 2007). "We demonstrate in epithelial tumour cells that while the action of IL-6 cytokines through their membrane receptors is attenuated, regulation by IL-6 via trans-signalling is established." (PMID 17987036, 2007). "To this end, we administered sgp130, which selectively inhibits IL-6 trans-signalling, or Hyper-IL-6, which magnifies trans-signalling, to mice carrying Colon26 tumours." (PMID 17987036, 2007). "Interleukin-6 (IL-6) is a pleiotropic cytokine that regulates the immune response, but also plays a role in promoting tumour growth and survival." (PMID 17224923, 2007). "In contrast, boosting IL-6 trans-signalling by administration of Hyper-IL-6 resulted in increased tumour control." (PMID 17987036, 2007). "The data suggest that the post-PDT tumour milieu contains the necessary components to establish effective IL-6 trans-signalling, thus providing a means for more effective tumour control." (PMID 17987036, 2007). "Tumor cells frequently express the receptor for IL-6, thus rendering them responsive to autocrine and/or paracrine IL-6-mediated stimulation." (PMID 17324269, 2007). "The post-PDT tumour milieu contains abundant amounts of IL-6 and other inflammatory mediators to which surviving cells within the treatment field do not respond directly because of PDT-induced degradation and inactivation of their membrane-bound IL-6Rα." (PMID 17987036, 2007). "We evaluated a panel of basal cytokines more commonly involved in the tumor control and progression (IL-1 beta, IL-6, IL-8, IL-10, IL-12, TNF-α) both in 144 healthy donors and in 55 patients affected by MRCC treated with IL-2 based regimens." (PMID 17953739, 2007).
tumor (continued). "Leucocytes respond to the tissue injury, enter the tumour environment, generate sIL-6Rα as well as IL-6 and thus allow the transmission of IL-6 signals in surviving tumour cells." (PMID 17987036, 2007). "We show the generation of IL-6 by PDT-treated tumour cells as well as by macrophages exposed to medium conditioned by these tumour cells." (PMID 17987036, 2007). "BesidesVEGF, other cytokines secreted by tumor cells are involved in the inhibition ofDC differentiation and maturation, among others are IL-6, IL-10, and M-CSF." (PMID 18320010, 2007). "They in turn produce various cytokines, such as tumor necrosis factor-α (TNF-α), IL-1, IL-4 and IL-6, which can induce apoptosis of tumor cells." (PMID 17177999, 2006). "This is in line with a recent study by Chow and co-workers which shows a correlation between elevated IL-6 levels in serum as well as in tumour tissues of NPC patients." (PMID 16995954, 2006). "High VEGF, IL-6, IL-10, TGFβ and M-CSF levels in the tumour microenvironment block dendritic cell differentiation and maturation." (PMID 16832418, 2006). "Firstly, that an elevated C-reactive protein identifies tumours capable of producing significant amounts of proinflammatory cytokines, in particular interleukin-6 and therefore with the potential for more rapid growth of tumour cells." (PMID 16523196, 2006). "mRNA levels of TNFα and IL-6 were unchanged in tumour-bearing mice compared with controls (both P>0.05)." (PMID 17047651, 2006). "Interleukin-6 is recognised as an autocrine growth factor for tumours, but also has a tumour suppressive role in promoting anti-tumour activity of macrophages." (PMID 17003778, 2006). "TNF, IL-6, and IL-8 can directly or indirectly promote tumor growth via induction of VEGF expression." (PMID 17096856, 2006). "In the present study, median IL-1β concentrations were 10–100-fold higher than IL-6 in the tumour tissue and there was a weak but significant correlation between tumour tissue IL-1β concentration and serum CRP." (PMID 17088911, 2006). "Precise localisation of pro-inflammatory cytokines such as interleukin-6 to tumour cells or inflammatory cells within the tumour, particularly in paraffin-embedded tissues, remains problematical." (PMID 17024120, 2006). "Tumour volume was correlated with C-reactive protein (r2=0.20, P=0.002), interleukin-6 (r2=0.20, P=0.002) and interleukin-10 (r2=0.24, P=0.001)." (PMID 17003778, 2006). "Tumour volume was weakly correlated with C-reactive protein (r2=0.20, P=0.002), interleukin-6 (r2=0.20, P=0.002) and interleukin-10 (r2=0.24, P=0.001)." (PMID 17003778, 2006). "The milk fermented by L. helveticus R389 was able to modulate the relationship between immune and endocrine systems (by IL-6 diminution), which is very important in oestrogen-dependent tumour and induced cellular apoptosis." (PMID 15987453, 2005). "In the present study, we attempted to assess interleukin-6 within the tumour using different methods of antigen retrieval and staining and the use of negative and positive controls." (PMID 15700032, 2005). "Milk fermented by this LAB induced not only a decrease of IL-6, but also an increase of regulatory cytokines, principally IL-10, and also induced cell apoptosis in the tumour." (PMID 15987453, 2005). "In comparison with the tumour control, all test groups showed a decrease of IL-6, a cytokine involved in oestrogen synthesis." (PMID 15987453, 2005). "Increased serum IL-6 levels have been detected in several tumor types, having a prognostic meaning for some of them." (PMID 15847702, 2005). "Confirmation of this will require direct comparison between the −174 G/C genotype and tumour IL-6 expression levels." (PMID 14735187, 2004). "The source of IL-6 in patients with NSCLC remains uncertain since both a variety of host cells and the tumour cells have been shown to produce IL-6." (PMID 15570310, 2004).